ALMS1 (ALMS1 centrosome and basal body associated protein)
Diseases named in the same sentence as ALMS1 in open-access papers (continued):
Sharing a sentence is not in itself a finding about the gene and the disease.
Alström syndrome (continued). "She had genetic testing done that revealed that she was homozygous for the ALMS1 gene and was diagnosed with Alstrom syndrome." (PMID 38883129, 2024). "Genetic testing was reviewed, which revealed that she was homozygous for the ALMS1 gene and was diagnosed with Alstrom syndrome." (PMID 38883129, 2024). "Alström syndrome (ALMS) is a vision disorder primarily characterized by CRD and hearing loss and is attributed to a mutation in ALMS1 gene, encoding ALMS1." (PMID 36830640, 2023). "Searching the literature for other rod/cone disease genes, we took note of Alms1, the gene disrupted in the Alström syndrome." (PMID 37252956, 2023). "Alström syndrome (AS) is a progressive multisystemic ultrarare autosomal recessive genetic disorder due to different genetic alterations on the ALMS1 gene in chromosome 2p13.1 (OMIM #203800, prevalence: 1–9 cases per million inhabitants)." (PMID 36263420, 2022). "The Alström Syndrome carried compound heterozygous ALMS1 ((NM_015120.4)) c.10079C>G (p.A3360G)/c.10323G>C (p.K3441N) mutations inherited from each parent." (PMID 36440223, 2022). "Patients with Alström syndrome and ALMS1 mutant mice are obese, but with increased insulin resistance that is disproportionate to body weight, adiposity, and fat distribution." (PMID 34759842, 2021). "Few LCA-associated genes like CEP290, ALMS1, IFT140, and IQCB1 also contribute to other syndromes such as Joubert syndrome, peroxisomal disease, Alstrom syndrome, Batten disease, and Senior Loken syndrome with similar ocular manifestations as observed in LCA." (PMID 33957996, 2021). "ALMS1 localizes to the basal body at the base of cilia leading to the classification of Alström Syndrome as a ciliopathy." (PMID 33793549, 2021). "Alström syndrome (AS; OMIM #203800) is a rare recessively inherited disorder caused by loss-of-function variants in the ALMS1 gene." (PMID 32867697, 2020). "A rare form of syndromic dilated cardiomyopathy (DCM) is the Alström syndrome (AS) [OMIM 203800] (prevalence 1.4 cases per 1,000,000), a multisystem disorder, inherited as autosomal recessive trait, caused by mutations in the ALMS1 (OMIM 606,844)." (PMID 32396277, 2020). "Alström Syndrome (ALMS; OMIM #203800) is an ultra-rare multisystem genetic disorder caused by pathogenic variants of ALMS1 gene." (PMID 32958032, 2020). "The patient with clearly visible ALMS1 cellular staining, although having unequivocal Alström syndrome, did show a later onset and more indolent course of visual symptoms." (PMID 28717663, 2017). "According to DNA microarray data, a probe set specific for the Alstrom syndrome gene (ALMS1) was among the probe sets with lowest signal intensities in HL cell lines compared to normal tissues." (PMID 28135309, 2017). "Here we investigated the role of Alms1 disruption in AT expansion and insulin responsiveness in a murine model for Alström Syndrome." (PMID 25299671, 2014). "Alström syndrome (AS, OMIM #203800) is a rare autosomal recessive disorder caused by mutations in Alström syndrome 1 gene (ALMS1; chromosome 2p13)." (PMID 22876109, 2012). "Other groups previously identified ALMS1 as the gene responsible for the autosomal recessive disorder, Alström syndrome, based on evidence from a balanced chromosomal translocation." (PMID 21453473, 2011). "ALMS1 is expressed in most tissues affected in Alström syndrome, including the organ of Corti, retinal photoreceptors, renal tubules, liver, and pancreatic islets." (PMID 22043170, 2011). "The Alms1 gene-trapped mouse model, Alms1GT/GT, exhibits most of the classic disease phenotypes found in individuals with Alström syndrome." (PMID 22043170, 2011). "A defective function of ALMS1 in the target tissues of insulin action, as well as in central nervous system is probably responsible for the clinical features of Alström Syndrome." (PMID 20108502, 2008).
Alström syndrome (continued). "Alstrom syndrome is a rare autosomal recessive genetic disorder caused by nonsense and frameshift mutations primarily in exons 8 (21%), 10 (23%), and 16 (40%) of the ALMS1 gene." (PMID 36077104, 2022). "Although ALMS1 gene mutations are associated with Alstrom syndrome (AS), the current patients did not exhibit typical syndromic features of AS." (PMID 33782391, 2021). "Reprogrammed fibroblasts from a patient with Alström syndrome and biallelic ALMS1 mutations also displayed absent ALMS1 immunostaining at the centrosome." (PMID 28982679, 2017). "Haplotype analysis showed that our patient and his sister shared only one allele in the ALMS1 region, meaning that the disorder shared by them is most likely not Alström syndrome." (PMID 21843323, 2011). "However, the knowledge that ALMS1 is a ciliary protein and plays a role in normal centrosome/basal body function and their associated intracellular trafficking events allows new hypotheses to be formulated and to make further progress in understanding and treating Alström syndrome." (PMID 22043170, 2011). "Alström syndrome (OMIM 203800) first described in 1959, is a rare autosomal recessive disorder caused by mutations in a novel gene of unknown function, ALMS1, located on the short arm of chromosome 2." (PMID 20108502, 2008). "Alström syndrome (OMIM 203800) was first described in 1959; it is a rare autosomal recessive disorder caused by mutations in a novel gene of unknown function, ALMS1, located on the short arm of chromosome 2." (PMID 20108502, 2008). "Alström syndrome (ALMS; OMIM #203800) is a rare autosomal recessive disorder caused by biallelic mutations in the ALMS1 gene, with an estimated global prevalence of approximately 1 in 1,000,000 individuals." (PMID 41466426, 2025). "Alström Syndrome (ALMS, OMIM 203800) is an ultra-rare genetic disorder resulting from biallelic loss-of-function mutations in the Alms1 gene on chromosome 2p13." (PMID 40676683, 2025). "Since ALMS1 is found in centrosomes, basal bodies, and cytosol in many organs, including retinal photoreceptors and the brain, the progressive development of multi-organ pathologies of Alstrom syndrome includes retinal dystrophy, neurosensory deficit, and type 2 diabetes mellitus." (PMID 36077104, 2022). "Moreover even in P2, whose cells showed normal ALMS1 staining, and who was recorded to have nystagmus and photophobia around 3 months old, visual acuity remained at 6/36 at the age of 24 years old, highly atypically for Alström syndrome." (PMID 28717663, 2017). "In P11, no ALMS1 staining was seen, in P16, staining was only equivocal, and in P2, it was nearly normal; however, the associated clinical syndromes were each typical of Alström syndrome." (PMID 28717663, 2017). "Alström syndrome (ALMS, OMIM #203,800) is a rare disease caused by mutations in the ALMS1 gene." (PMID 38062477, 2023). "Determining how ALMS1 regulates cell migration and adhesion processes such as EMT is critical to understanding how multi-organ fibrosis occurs in Alström syndrome." (PMID 36325276, 2022). "In the case of Alström syndrome, dilated cardiomyopathy is a phenotype present in approximately two-thirds of patients, so it would be expected that ALMS1 depletion was not enough for the appearance of this symptom." (PMID 36325276, 2022). "Cilia in Alms1 mutant mice and fibroblasts isolated from Alström syndrome patients appear grossly normal even when there is no visible antibody labeling for ALMS1 protein." (PMID 33793549, 2021). "Although, ALMS1 gene which belong to Alström syndrome was not tested genetically specially by the patients (F1-II:1, F3-II:1, and F3-II:2) which have hearing disturbances, the disease-causing gene of BBS we identified was co-segregated with the family members and phenotype." (PMID 33777945, 2021).
Obesity (36 papers, 2008 to 2026). Accumulation of substantial excess body fat. "Assessed on 45% fat diet to promote adipose expansion, global Alms1 KO caused hyperphagia, obesity, insulin resistance, dyslipidaemia, and fatty liver." (PMID 38583571, 2024). "Together, this argues that mutations in ALMS1 cause adipose tissue dysfunction, which in turn drives insulin resistance, type 2 diabetes mellitus, and obesity in ALMS patients." (PMID 34759842, 2021). "Taken together, these data show that ALMS1 mutation causes adipose tissue dysfunction, leading to the development of obesity, extreme insulin resistance, and early-onset type 2 diabetes mellitus in ALMS patients." (PMID 34759842, 2021). "In people, mutations in the ALMS1 gene are most frequently associated with multisystem disease, including retinal degeneration, obesity, neurosensorial deafness, type 2 diabetes as well as cardiomyopathy." (PMID 33639992, 2021). "OB1–5, carrying two rare missense variants in ALMS1, displays hyperphagia in addition to severe early-onset obesity." (PMID 31488071, 2019). "Chow-fed female mice with a truncating mutation (foz) in the Alstrom syndrome 1 (ALMS1) gene, exhibit disordered appetite regulation and develop obesity, diabetes, and simple steatosis." (PMID 24192824, 2013). "In addition, the results also indicate a link between selected metabolites - in particular, BCAA and ketone bodies - and disorders such as overweight/obesity or hyperglycemia observed in heterozygous carriers of ALMS1 and BBS gene variants." (PMID 41312125, 2025). "In a prior study, MCC950 was gavaged daily 5 days/week (20 mg/kg/day, in saline) for 8 weeks in female foz/foz mice (which are hyperphagic due to a mutation in the Alms1 gene and develop severe obesity and hyperglycemia) following 16 weeks on an atherogenic diet." (PMID 36641116, 2023). "It remains plausible that the primary cilium or basal body dysfunction due to defective ALMS1 among homozygous carriers contributes to many aspects of the AS phenotype including obesity, retinal dystrophy, hearing loss, kidney dysfunction, neurological disturbances, and fibrosis." (PMID 33981653, 2021). "Elucidating the function of the mutated gene, ALMS1, is critical for the development of specific treatments and may uncover pathways relevant to a range of other disorders including common forms of obesity and type 2 diabetes." (PMID 30421101, 2019). "In the literature, no data are available on fertility in female AS patients, and only one study in mice has suggested that female Alms1 foz/foz mice were fertile at an early age and became infertile after the development of obesity due to an anovulatory state." (PMID 36263420, 2022). "ALMS1 mutant mice present with hyperglycemia, insulin resistance and hyperleptinemia prior to the development of obesity." (PMID 34759842, 2021). "Mouse Alms1 mutants show similar phenotypes as human patients, including obesity, retinal dysfunction, hyperinsulinemia, and delayed onset hearing loss." (PMID 33793549, 2021). "Remarkably, ALMS1 expression in adipose tissue completely rescued obesity, adipocyte hypertrophy, glucose tolerance, and insulin sensitivity." (PMID 34759842, 2021). "Targeted panel for ciliopathies, retinal diseases, cardiomyopathy or even obesity should include ALMS1 gene." (PMID 32958032, 2020). "Here, we demonstrate that disruption of Alms1 induces alterations of adipocyte morphology and gene expression profile in 6 week old mice, before the onset of obesity and hyperinsulinemia." (PMID 25299671, 2014). "It has been hypothesized that loss of functioning ALMS1 could impact the cilia on hypothalamic neurons and lead to alteration in behavior and energy homeostasis, through abnormal perception of appetite and satiety cues, such as leptin, resulting in overeating and obesity." (PMID 22043170, 2011).
Obesity (continued). "Notably, Alms1 KO rats develop hyperleptinemia as early as 7 weeks, prior to the onset of obesity, implicating ALMS1 in early leptin regulation and metabolic signaling." (PMID 41691606, 2026). "The greater metabolic derangement and obesity induced by Alms1 KO in female compared to male mice, although not previously discussed, is consistent with the greater body weight increase reported in females than males in three prior Alms1 KO mouse models." (PMID 38583571, 2024). "Additionally, we identified one individual with biallelic LoF variants in ALMS1 diagnosed with EOSRD, obesity, and hypotonia." (PMID 29186038, 2017). "Presently, a map of genes causing obesity in pleiotropic syndromes (SNRPN gene for the obesity in PWS, GNAS1 gene in PHP1A, ALMS1 gene in ALMS, FMR1 gene in FXS, and others), has been established." (PMID 25866584, 2015). "We appreciate that heterozygous mutations in genes such as ALMS1, BBSs, LEPR, POMC, and PCSK1 have not been shown to be sufficient to cause the disease of obesity, except for the complete loss-of-function mutations of PCSK1, but not for POMC or LEPR mutations." (PMID 37835041, 2023). "To illustrate, ALMS1 gene is related with an “Alstrom syndrome 1” where obesity is a frequent clinical outcome in patients, but, direct evidence of linking ALMS1 with obesity is not reported in literature." (PMID 26886906, 2016). "Diastolic dysfunction has been associated with non-cardiac drivers, such as hypertension, diabetes and obesity, and we have reported that the line of global Alms1 KO mice used in this study is, like other global KO models described previously, obese and insulin resistant." (PMID 38756069, 2024). "This study showed that ALMS1 deficiency may promote anovulatory infertility via elevated androgens through a cooperation between ALMS1 and the luteinizing hormone (LH)/chorionic gonadotropin receptor, which induced a PCOS and obesity phenotype characterized by anovulation and hyperandrogenemia." (PMID 36263420, 2022). "Male Alms1 MSC KO mice, although not exhibiting the obesity of Alms1 global KO mice, also showed IR." (PMID 38583571, 2024). "Several hallmark features of ALMS such as cardiomyopathy, widespread fibrosis, and severe obesity with metabolic syndrome are known to be related to deregulation of TGF-β/BMP signaling; however, the possible connection between this pathway and the ALMS1 protein has not been extensively studied." (PMID 33598462, 2021).
ciliopathy (27 papers, 2011 to 2025). A genetic disorder of the cellular cilia or the cilia anchoring structures, the basal bodies, or of ciliary function. "Mutations in ALMS1 were historically classified as causing a “ciliopathy” due to the protein’s centrosomal localization and the associated defects in ciliary formation, maintenance, and signaling." (PMID 41466426, 2025). "We show that the carrier frequency even for LOF variants in established ciliopathy disease genes (e.g. ALMS1), is higher than expected based on disease prevalence (carrier frequency of ~1/79 for a disease prevalence of ~1/100’000-1’000’000)." (PMID 36550190, 2023). "In contrast to the locus heterogeneity associated with BBS, Alström syndrome (AS) is a monogenic ciliopathy associated exclusively with variants in ALMS1 (OMIM#606844)." (PMID 34365092, 2021). "Mutations in ALMS1 are known causal of AS [OMIM 203800], a rare autosomal recessive ciliopathy, which has been associated with cardiomyopathy, suggesting ALMS1 as the potential candidate causal gene in our proband." (PMID 34387706, 2021). "As far as we know, ALMS represents a particular entity within ciliopathies since, it is a monogenic syndrome caused by mutations in the ALMS1 gene (HGNC:428)." (PMID 33598462, 2021). "Other ciliopathy-associated proteins have been linked to DDR signalling but the potential role of ALMS1 in this process remains to be investigated." (PMID 30421101, 2019). "The specific localisation of ALMS1 to the proximal ends of centrioles is unusual for a ciliopathy-associated protein." (PMID 30421101, 2019). "ALMS1 loss-of-function has been linked to defects in primary cilium formation, positioning and maintenance, leading to AS being classified as a ciliopathy." (PMID 30421101, 2019). "Exome‐wide sequencing in this patient showed only a common polymorphism in a minor ALMS1 splice variant, but did delineate a range of other sequence variants present in known ciliopathy genes." (PMID 28717663, 2017). "The shared clinical phenotype of BBS and AS ciliopathies suggests related roles for ALMS1 and BBSome proteins in cilia function and protein transport." (PMID 34365092, 2021). "We also observed that knockdown of ciliopathy genes ALMS1, BUBR1 [BUB1B], IFT80, NPHP1, NPHP8 [RPGRIP1L], TCTN2, TMEM216 and TUB retarded neuronal migration." (PMID 26206566, 2015). "The identification of ALMS1 as a ciliary protein explains the range of observed phenotypes and their similarity to those of other ciliopathies such as Bardet-Biedl syndrome." (PMID 22043170, 2011). "The role of ALMS1 in skeletal deformities remains unexplored, but skeletal issues are common in ciliopathies, suggesting ciliary protein complexes may influence cell polarity." (PMID 40676683, 2025). "Regarding conception, considering the AS part of genetically determined ciliopathies, ALMS1 dysfunction may be involved in embryo implantation and pregnancy development." (PMID 36263420, 2022). "The recovery of full-length BBS2 and ALMS1 expression and correction of anatomical and functional ciliary defects suggests TRIDs are a potential therapeutic option for the treatment of nonsense-mediated ciliopathies." (PMID 34365092, 2021). "No second, known ciliopathy mutation was found in the other patient, who had one LoF ALMS1 mutation." (PMID 28717663, 2017). "Our strategy, based on first applying several filters to ciliary variants and using many of the bioinformatics tools available, allowed us to identify causal mutations in BBS2, ALMS1 and CRB1 genes in four families, thus confirming the molecular diagnosis of ciliopathy." (PMID 28800606, 2017). "These phenotypic differences between patients could be attributed to interactions with other genes inherited independently from the ALMS1 gene, as has been described in other ciliopathies with retinal degeneration, or could be attributed to environmental factors." (PMID 22876109, 2012).
ciliopathy (continued). "CFAP45 and PROM1 are found in both atypical and secondary ciliopathies, whereas TTC26, SCLT1, DNAJB11, DYNC2LI1, ALMS1, IFT80 and IFT74 are shared between primary and atypical ciliopathies." (PMID 37542408, 2023). "Although ALMS has traditionally been classified as a ciliopathy, accumulating evidence suggests that ALMS1 also exerts important non-ciliary functions in intracellular trafficking, cytoskeletal organization, and metabolic regulation." (PMID 41466426, 2025). "Recently, two cases affected with nonBBS ciliopathy phenotypes were associated with retrotransposon insertions; a L1 in exon 7 of CC2D2A and an Alu in exon 16 of ALMS1." (PMID 30484961, 2019). "The recovery of full-length BBS2 and ALMS1 expression and correction of anatomical and functional ciliary defects in BBS2Y24*/R275* and ALMS1S1645*/S1645* fibroblasts suggest TRIDs are a potential therapeutic option for the treatment of nonsense-mediated ciliopathies." (PMID 34365092, 2021). "However, the precise role of the ALMS1 protein remains uncertain and no clear links have been established with other ciliopathy proteins." (PMID 30421101, 2019). "In our literature review of a total of 161 articles, only a single ciliopathy case was reported in the IFT140 gene, and none in any BBS genes or the ALMS1 gene." (PMID 40225151, 2023).